GTF2H2C (GTF2H2 family member C)
Description:
Component of the core-TFIIH basal transcription factor involved in nucleotide excision repair (NER) of DNA and, when complexed to CAK, in RNA transcription by RNA polymerase II.
Tractability: PROTAC: ubiquitination databases record sites on it.
Gene: Protein-coding gene on chromosome 5 (69,558,392 to 69,595,221, forward strand). Ensembl gene ENSG00000183474.
Subcellular location: Nucleus
Subcellular location (Human Protein Atlas): Nuclear speckles
Gene Ontology:
Molecular function: protein binding; zinc ion binding
Biological process: DNA repair; DNA-templated transcription; nucleotide-excision repair
Cellular component: nucleus; transcription factor TFIIH core complex
Genetic constraint (gnomAD): Loss-of-function variants: 1 observed, 7.52 expected, observed/expected ratio (o/e) 0.13, 90% interval 0.046 to 0.63. That is too few expected variants to judge how well the gene tolerates losing a copy. Missense variants: 28 observed, 73.02 expected, observed/expected ratio (o/e) 0.38, 90% interval 0.28 to 0.53. Synonymous variants: 9 observed, 23.18 expected, observed/expected ratio (o/e) 0.39, 90% interval 0.23 to 0.68.
Homologues: Orthologues: mouse Gtf2h2 (97% identical), rat Gtf2h2 (96% identical), macaque GTF2H2 (88% identical), tropical clawed frog gtf2h2 (83% identical), zebrafish gtf2h2 (81% identical), Drosophila melanogaster Ssl1 (52% identical), Caenorhabditis elegans gtf-2H2C (41% identical). Paralogues in human: GTF2H2 (99% identical).
Diseases named in the same sentence as GTF2H2C in open-access papers:
GTF2H2C is named in the same sentence as 5 diseases in open-access papers, as found by Europe PMC text mining. Sharing a sentence is not in itself a finding about the gene and the disease.
GTF2H2C shares sentences with these, for which no sentence is quoted: Fanconi anemia (1 paper); glioma (1); lung adenocarcinoma (1); Lung Squamous Cell Carcinoma (1); tumor (1).